IGF1 (insulin like growth factor 1)
Diseases named in the same sentence as IGF1 in open-access papers (continued):
Sharing a sentence is not in itself a finding about the gene and the disease.
Obesity (continued). "Hormonal dysregulation, proinflammatory cytokines, myokines (including insulin-like growth factor 1 (IGF-1), myostatin, and irisin), and adipokines (including adiponectin and resistin) constitute crucial factors in muscle homeostasis and the pathogenesis of sarcopenic obesity." (PMID 35956299, 2022). "A negative correlation between either GH or IGF-1 and the ratio between truncal fat mass and appendicular skeletal muscle mass has been reported in subjects with obesity, suggesting that altered GH/IGF-1 status may play a role in determining the sarcopenic obesity phenotype." (PMID 35565781, 2022). "Moreover, expression of IGF-1 is lower in humans with obesity specifically within skeletal muscle, and which could more directly, when compared to plasma IGF-1, contribute to attenuating muscle protein synthesis in humans with obesity." (PMID 35350688, 2022). "Therefore, the purpose ofthis study was to investigate the influences the effect of circuit exercisetraining for 12 weeks on cardiovascular risk factors, vascular inflammatorymarkers, and insulin-like growth factor-1 (IGF-1) in elderly obesity women withsarcopenia." (PMID 39076242, 2022). "Therefore, presence of lower IGF-1 in plasma, or more importantly within skeletal muscle, in obesity may have key role in mediating lower protein synthesis in muscle of humans with obesity." (PMID 35350688, 2022). "Thus, the increased macrophage presence in adipose tissue in obesity could explain, at least in part, the significant increase observed in IGF1 levels after the ingestion of a HFD." (PMID 36353242, 2022). "Activation of PPAR-δ by FA components of a high-fat diet, hormonal imbalance related to obesity including insulin/IGF-1 resistance and adiponectin decline, increase in inflammation, and metabolic alteration by high-fat diet-induced obesity and microbiota dysbiosis could be named." (PMID 33827616, 2021). "Moreover, insulin signaling dysfunction in obesity caused by impaired binding of insulin-like growth factor-1 (IGF-1) to insulin receptors on osteoblasts also had a negative impact on bone remodeling." (PMID 34445970, 2021). "Moreover, hyperinsulinemia may exert potent proliferative effects, either directly or by cross-reacting with the insulin-like growth factor 1 (IGF-1) receptor thus increasing the risk of cancer in obesity and type 2 diabetes." (PMID 33555509, 2021). "Radiation-induced IGF-1 signaling perturbations offer an explanation to several of the late effects observed in humans including the systemically coordinated failure of the internal organs and development of diabetes, obesity, metabolic syndromes, and cardiovascular diseases." (PMID 33807089, 2021). "Moreover, weight loss in individuals with obesity after a low-energy liquid diet was associated with improvements in insulin sensitivity but IGF-1 was not significantly modified." (PMID 32806629, 2020). "Increased IGF-1 levels in obesity have a negative effect and cause GH suppression." (PMID 32586279, 2020). "In addition, excluding the interference of obesity, IGF-1 might be elevated before initiation of puberty." (PMID 32727432, 2020). "Moreover, vessel-dependent effects of insulin and insulin-like growth factor-1 on vascular tone and Akt activation may have implications in treating obesity-related vascular disease." (PMID 30295509, 2019). "Among the factors that link obesity to carcinogenesis are the activation of the insulin/IGF-1 pathway, increased concentrations of pro-inflammatory cytokines (TNF-α, IL-1 and IL-6) and their influence on adipocytokines, and dyslipidemia, which is often associated only to obesity." (PMID 31703601, 2019). "Moreover, whether IGF-1 has vasorelaxant effects in resistance arteries and the effect of obesity on these responses is also unclear." (PMID 30295509, 2019).
Obesity (continued). "Furthermore, serum levels of insulin and IGF-1 which increased in obesity and/or metabolic disease patients may be facilitate tumorigenesis, proliferation, survival and appear to be a major mechanism linking obesity to cancer." (PMID 28373897, 2017). "This approach revealed that most of the components of the GH/insulin/IGF1 regulatory axis are present in PGs, where their expression pattern is altered under obesity conditions and after an acute insulin treatment (e.g. Igfbp3), which might have some pathophysiological implications." (PMID 28244645, 2017). "Thus, the obesity of ksr2−/− mice cannot be ascribed to the suppression of IGF-1 expression." (PMID 27561547, 2016). "However, no studies regarding the levels of IGF-1 in morbidly obese patients with renal injury associated with obesity have been conducted." (PMID 27138941, 2016). "It must be considered that multiple factors interact to control IGF-1 levels, many of which are disturbed in T2D, namely: increased inflammatory cytokines, decreased hepatic insulin action due to resistance, concomitant changes in IGFBPs, and the effects of obesity." (PMID 26733412, 2016). "IGF-1 is a nontraditional factor which has been linked to atherosclerosis and obesity." (PMID 24616825, 2014). "Thus, targeting IGF-1 and NF-κB in the context of obesity and elevated bioavailable IGF-1 may be an effective strategy for mimicking the anticancer effects of CR and breaking the obesity-pancreatic cancer link." (PMID 24804677, 2014). "However, there was evidence of a proliferative effect on WiDr cells at extremely low concentrations of 5-FU and oxaliplatin, alone or with IGF-1, as may occur in obesity." (PMID 24396438, 2014). "In addition, close relation to biochemical markers including lipid profiles, hepatic enzymes, adipokines, and IGF-1 suggests that these factors could contribute to obesity phenotypes." (PMID 24872812, 2014). "Calorie restriction (CR) prevents obesity and has potent anticancer effects that may be mediated through its ability to reduce serum growth and inflammatory factors, particularly insulin-like growth factor (IGF)-1 and protumorigenic cytokines." (PMID 24804677, 2014). "Obesity is also associated with BMD because of the conversion of androgen to estrogen, which improves bone mass in both men and women and maintains healthy plasma levels of insulin and regulating factors including insulin-like growth factor-1, leptin, and adiponectin." (PMID 24222888, 2013). "Furthermore, it should be noted that evaluation of the plasma level of free or total IGF-1 in obesity might be complicated by factors such as IGF binding proteins and fat mass." (PMID 23630454, 2013). "Together, the altered hormonal and inflammatory milieu of obesity may contribute significantly to cancer growth and progression via promoting mitogenesis (e.g., leptin, IGF-1, insulin), angiogenesis (e.g., VEGF, IL6, IL8), and invasion (e.g., leptin, IL6, PAI-1, CCL5, CCL2)." (PMID 23573093, 2013). "Children with growth retardation showed significantly lower levels of IGF-1 and, among the DXA parameters, had a lower BMC Spine, aBMD Spine, BMAD, and BMD TBLH compared to children with obesity." (PMID 40364018, 2025). "Mean levels of growth factors IGF1, HGF, and PDGF-BB remained consistent across individuals with normal weight, overweight and obesity." (PMID 41150772, 2025). "Conversely, low circulating adiponectin in maternal serum, a feature of obesity and GDM, stimulates fetal growth by activating the placental insulin/IGF-1/mTOR signaling pathway." (PMID 40362828, 2025). "Surprisingly, laminitis reported in this study was not linked to obesity but associated with insulin levels <20 mU/L, lower body weight, and glucose levels, along with higher concentrations of albumin, catalase, glucose, insulin, and IGF-1 compared to obese mares." (PMID 40901060, 2025).
Obesity (continued). "Thus, an attenuated circulating total and free IGF‐1 response to exercise in individuals with obesity may limit the full therapeutic potential of exercise to improve metabolic function, muscle and cardiovascular health, and cognitive performance in these individuals." (PMID 40574473, 2025). "In addition, there is evidence suggesting that obesity is associated with lymph node metastases after RP, owing to the deranged prostatic microenvironment and cellular DNA caused by inflammatory factors (IL-6, IL-8, VEGF, leptin) and altered insulin-IGF-1 axis." (PMID 40364176, 2025). "A 5:2 diet with a 75% calorie restriction over six months in premenopausal women with obesity dramatically elevated IGFBP-1 and decreased IGF-1." (PMID 41439931, 2025). "Under disease states, obesity/diabetes attenuates catecholamine and FGF21 responsiveness; however, endurance training can still improve myocardial mitochondrial function via the IGF-1 pathway." (PMID 41000109, 2025). "Previous studies have investigated the relationship between obesity and IGF-1 levels and found a dysregulation of IGF-1 pathways in individuals with obesity, suggesting a potential link between body fat and Klotho." (PMID 40060377, 2025). "This diminished response is accompanied by a lower serum IGFBP‐3 response, highlighting a coordinated (dys) regulation of both IGF‐1 and IGFBP‐3 responses to exercise in individuals with obesity." (PMID 40574473, 2025). "Previous studies have demonstrated that ghrelin can inhibit the reduction of obesity-induced myocardial injury by influencing the lncRNA H19/miR-29a/IGF-1 signaling pathway and the HOTAIR/miR-196b/IGF-1 signaling pathway." (PMID 39860298, 2025). "The activation of the IGF1/PI3K/mTOR/S6K1 pathway mediates the formation of SGs and promotes the development of obesity‐related PDAC." (PMID 40211955, 2025). "In both human obesity and DIO rat models, the highly pulsatile GH secretion is generally decreased, while the effects on IGF-1, the major mediator and marker of GH action over time, and peripheral tissues have been far from concordant." (PMID 41091300, 2025). "Elevated IGF-1 and decreased IGF-binding proteins are observed in both obesity and PCOS, suggesting shared mechanisms linking metabolic and reproductive endocrine disorders to endometrial overgrowth." (PMID 41514656, 2025). "Our findings accentuate circulating MEG3/miR-27a/IGF1/IGFBP3, especially miR-27a as valuable markers for the early detection of obesity-related CRC." (PMID 38704452, 2024). "Overall, the simultaneous effects of diabetes and obesity on IGF-1 levels are complex, as changes in the GH/IGF-1 axis induced by obesity oppose those triggered by metabolic processes in Type 2 Diabetes Mellitus (T2DM)." (PMID 39578883, 2024). "This study, in a novel way, tracks the actions and impacts of IGF-1 and IGF-2 on the human body over the course of a lifetime, considering disturbed metabolism in the course of obesity." (PMID 38612776, 2024). "Among the most important are leptin and adiponectin (which, respectively, increase and decrease in obesity), tumor necrosis factor (TNF) α, interleukin (IL)-6, and insulin-like growth factor-1 (IGF-1), CXCL12, steroid hormones, and lipids." (PMID 38339271, 2024). "The most interesting finding in this study was that serum CES1 levels were significantly associated with lipid metabolism (ALT, AST, TG, TC, LDL-C), glucose metabolism (FBI, HOMA-IR) and obesity-related secreted proteins (adiponectin, leptin, GDF15, IGF-1)." (PMID 39227971, 2024). "Research has established an association between diabetes and increased cancer incidence, with elevated insulin and insulin-like growth factor 1 (IGF-1) levels in diabetes and obesity promoting cell growth." (PMID 39594685, 2024). "Obesity and IGT contribute to enhanced IGF-1 response, which facilitates cancer development by inhibiting apoptosis and promoting cell proliferation." (PMID 37511200, 2023).
Obesity (continued). "In our previous work, we demonstrated that the pre-clinical anti-obesity effect of the probiotic BPL1TM, the postbiotic BPL1TM HT and the purified LTA from BPL1TM was dependent on the insulin/IGF-1 signaling pathway." (PMID 38136226, 2023). "In obesity, T2DM and NAFLD, hyperinsulinemia and dysregulated insulin signaling occurs when insulin and IGF-1 bind to their respective receptors and activate PI3K/Akt signaling, a key oncogenic pathway for metabolism, cell growth and cell survival." (PMID 37361533, 2023). "However, when vitamin D levels decrease (if IGF1 fails to increase vitamin D level or due to other causes) hypovitaminosis D-associated obesity might occur." (PMID 37892272, 2023). "In obesity, multiple adipokines such as TNF-α regulate adipocyte homeostasis, disturb the IGF-1 synthesis, and impair its signaling." (PMID 36991247, 2023). "High fat diet (HFD)-induced obesity altered the circulating IGF cascade and increased circulatory level of total IGF-1, IGF-2, free IGF-1, and IGFBP3 in rodent and clinical trials." (PMID 36691085, 2023). "Four out of 56 cats had IGF‐1 concentrations >1000 ng/ml, resulting in a 7.1% (95% confidence interval 1.9%–17.2%) HST prevalence rate in non‐diabetic cats with overweight/obesity." (PMID 38053473, 2023). "Fourteen months later, he had partial resolution of the motor deficit but developed learning difficulty along with obesity, stunted height (3rd percentile), and high ACTH and low IGF-1 at the testing time." (PMID 36843696, 2023). "Independent from obesity, expression of GHR, IGF-1 and IGFBP-3 was related to AT dysfunction,and increased insulin levels." (PMID 36384443, 2022). "Comparing the mean values of the cohort, children with overweight/obesity were significantly taller compared to lean children and also the serum levels of GHBP, IGF-1 and IGFBP-3 appeared to be increased in children with overweight/obesity." (PMID 36384443, 2022). "Obesity mixed with OSAHS, meanwhile, creates a superposition effect, and subsequent drop in IGF-1 levels." (PMID 36120463, 2022). "Total IGF-1 and IGFBP3 concentrations in subjects with obesity are mildly elevated, as we observed in this study, but free IGF-1 levels are increased." (PMID 35412268, 2022). "Early-pubertal girls with obesity also had significantly higher values (p < 0.05) for BMI-SDS, leptin, IGF-1, IGFBP3, insulin and HOMA-IR, LH, ratio LH/FSH, ACTH, DHE-S, androstenedione, testosterone and free testosterone levels than control group." (PMID 35412268, 2022). "In adults with obesity and/or MAFLD, serum IGF1 levels were lower in those with higher degrees of inflammation and higher stage of fibrosis, and the serum IGF1/IGFBP-3 ratio decreased with increasing fibrosis." (PMID 36557260, 2022). "In the reverse MR analysis, we also observed effects of BMI (both childhood and adult) on obesity-related biomarkers, such as CRP, IGF1, insulin, leptin, and TNFR2." (PMID 36253437, 2022). "Pathway analysis revealed that obesity alters small EV miRNAs that target inflammatory (SERPINF1, death receptor and Gαi) and growth pathways (Wnt/β‐catenin, PTEN, PI3K/AKT and IGF‐1)." (PMID 35293040, 2022). "We observed that gene expression of GHR and IGF-1 in adipocytes and expression of IGFBP-3 in SVF cells was decreased in children with overweight/obesity compared to lean children." (PMID 36384443, 2022). "Serum GHBP levels were increased in children with overweight/obesity throughout childhood, while for IGF-1 levels and the IGF-1/IGFBP-3 molar ratio obesity-related elevations were detectable until early puberty." (PMID 36384443, 2022). "The obesity- and inflammation-related gene (IL-6, TNF-α, IGF-1, leptin, AP2/FABP4, AMPK-α2, β3AR, and PPAR-γ) expressions in the liver and epididymal adipose tissue were reduced in the PHPB-treated group." (PMID 35386305, 2022).
Obesity (continued). "High leptin levels in aging and obesity upregulate the proinflammatory cytokines IL-6 and TNF-α, reducing insulin-like growth factor 1 (IGF1) activity and decreasing their anabolic actions on skeletal muscle." (PMID 34676021, 2021). "Our findings are in marked contrast to those reported in children with idiopathic, hyperleptinemic obesity who usually have normal, or increased IGF1 serum levels, whereas weight loss in these children is typically associated with either a decrease or no change in IGF1 levels." (PMID 34002033, 2021). "IGF1 and IGF2 are highly expressed in CRC, and a variety of metabolic disorders such as obesity, dyslipidemia, hyperinsulinemia, and glucose homeostasis are common in these patients, making the IGF system a biomarker of human CRC susceptibility and prognosis." (PMID 34422629, 2021). "Means of IGF-1 and IGFBP3 in the undernutrition group were significantly lower than means in the eutrophic and obesity groups." (PMID 34684579, 2021). "We then utilized the PPI network to predict the mechanism of CHRDL1 in inducing obesity of PCOS patients, and the BMP4 signaling and IGF1 were identified." (PMID 33910166, 2021). "Until adolescence, children with obesity are taller independent of familial predisposition, which is attributable to increased birth size with subsequent growth acceleration until puberty with concomitant elevation of IGF-1 and metabolic alterations such as hyperinsulinemia." (PMID 34386750, 2021). "To test the hypothesis that selenium supplementation might confer MR-like benefits to mice by reducing circulating IGF-1 levels, we fed an otherwise normal high-fat diet containing sodium selenite to mice and assessed whether, like MR, this intervention protects against diet-induced obesity." (PMID 33783357, 2021). "Indirectly, the increased insulin levels inherent to obesity lead to increased circulating oestrogen and the ensuing decrease in IGFBP1, a negative regulator of IGF1." (PMID 32069845, 2020). "In obesity and metabolic syndrome (MetS), there is foremost dysregulation of IGFBP secretion resulting in changes in the levels of free IGF-1." (PMID 33905470, 2020). "High fat diet (HFD)-induced obesity has been shown to increase the expression of IGF2 in adipose tissue and to inhibit the effects of IGF1 in chondrocytes, while IGF1 stimulates adipose tissue proliferation." (PMID 32849298, 2020). "On the other hand, the depletion of SIRT6 in a neuron-specific manner lowered plasma growth hormone (GH)/insulin-like growth factor-1 (IGF-1) levels and decreased hypothalamic POMC expression, which led to postnatal growth retardation and obesity." (PMID 32143417, 2020). "ANGPL3, DPPIV, IGF1 and most of the IGF-binding proteins, all known to be secreted from the adipose tissue in relation to obesity and to pathological lipoprotein and lipid metabolism, were elevated in KO vs. WT mice." (PMID 31349725, 2019). "To examine the temporal effect of obesity on insulin and IGF-1-mediated phosphorylation of the key signalling kinase Akt, we performed in vivo administration of either insulin or IGF-1 to HF and LF fed mice after 2, 5 and 16 weeks." (PMID 30295509, 2019). "Obesity increases blood insulin levels and decreases IGFBP1 concentration, resulting in a rise in IGF1 levels." (PMID 31623387, 2019). "In addition, increased insulin-like growth factor-1 level which might explain the obesity-carcinogenesis connection was found not to be associated with lung cancer." (PMID 29866064, 2018). "High serum levels of insulin and insulin-like growth factor 1 (IGF-1), adipose tissue dysfunction and inflammation, and nutrient-replete circulation constitute several of the mechanisms by which obesity supports malignant cell growth." (PMID 28959684, 2017). "There is an inverse relation between BMI and total IGF-1 levels and a deregulation of growth hormone/IGF-1 signaling in obesity." (PMID 28288611, 2017).